IL13 (interleukin 13)
Diseases named in the same sentence as IL13 in open-access papers (continued):
Sharing a sentence is not in itself a finding about the gene and the disease.
helminth infection (continued). "Both IL-13 and IL-33 have been implicated in type 2 imprinting of macrophages or ILC2 during helminth infection, respectively." (PMID 36065058, 2022). "In vivo blockade of IL-10 signalling during helminth infection resulted in an expansion of IFNγ+ and Tbet+ Th1 cells in the small intestine and a coincident decrease in IL-13, IL-5 and GATA3 expression by intestinal T cells." (PMID 35428872, 2022). "While Th2 cell metabolism is regulated by mTOR and Akt and engages glycolysis, ILC2s at barrier sites take up long-chain fatty acids and preferentially metabolize fatty acids to fuel OXPHOS through FAO, promoting IL-13 expression during helminth infections." (PMID 36301303, 2022). "During helminth infections, IL-4 and IL-13 stimulate goblet cell hyperplasia, increasing mucin secretion which helps expel intestinal worms." (PMID 36569914, 2022). "Tuft cells are the primary producers of IL-25 in the small intestine, undergo hyperplasia in response to IL-13 during helminth infection, and can be identified by their unique expression of DCLK117,20–22." (PMID 35534698, 2022). "IL-4Rα signaling is crucial for the accumulation of GATA3+ Tregs in the inflamed intestine during helminth infections; therefore we analyzed the Th2 cytokines IL-4, IL-5, and IL-13 secreted by LPMCs in the colon." (PMID 34336843, 2021). "In summary, these data demonstrate a broad role for IL-13 in regulating type 2 immunity and epithelial cell function during acute helminth infection in the lung." (PMID 34127548, 2021). "In the lung, IL-33 participates in the activation of most of the inflammatory processes in which ILC2s are involved; it does so by inducing the expression of IL-5 and IL-13, mainly in models of upper airway inflammation or helminth infection." (PMID 34759931, 2021). "CD4+ Th2 cells producing IL-4, IL-5, and IL-13 direct cellular immunity in mucosal tissues to maintain barrier integrity after helminth infection." (PMID 34106992, 2021). "Its activation in this tissue induces similar effects as those in the lung in terms of the induced expression of IL-5, IL-13, amphiregulin, CSF-1 and IL-9, leading to proliferation and promotion of a defense response against helminth infections." (PMID 34759931, 2021). "Helminth infections usually trigger a Th2 immune response in the host, by releasing cytokines such as IL-4, IL-5, IL-13 and IL-33." (PMID 34324507, 2021). "Another neuropeptide, Calcitonin gene-related peptide (CGRP), suppresses IL-33- and NMU-activated ILC2s proliferation and IL-13 production but promotes IL-5 secretion during helminth infection." (PMID 34938670, 2021). "We used a CD2/IL-13 dual fluorescent reporter mouse for in vivo imaging of ILC2s and Th2 T cells in real time following a type 2 priming helminth infection or egg injection." (PMID 34484215, 2021). "In the small intestine, the accumulation of ILC2s and production of IL-13 upon helminth infection or malnutrition conditions are dependent on fatty acids oxidation (FAO), as a process required to obtaining energy." (PMID 34759931, 2021). "The host showed mainly the Th2 type of immune response against helminth infection, characterized by the secretion of cytokines, such as IL-4, IL-5 and IL-13." (PMID 34930417, 2021). "A vitamin A-deprived diet leads to IL-13-producing ILC2 expansion under helminth infection to eliminate the worms, probably via increased acquisition and utilization of fatty acids." (PMID 33995407, 2021). "Vitamin A deficiency (VAD) in mice leads to increased expression of IL-5, IL-13 and IL-4 by ILC2s in the small intestine upon helminth infection." (PMID 34759931, 2021). "The type 2 cytokines IL-5 and IL-13 are also secreted early during a helminth infection by innate lymphocytes (ILC2) in response to the release of IL-33 and TSLP from mucosal epithelial sensor cells." (PMID 34083746, 2021).
helminth infection (continued). "In several helminth infections, IL-4, IL-13 and IL-5 producing Th2 cells are related to the most important effector mechanisms in adaptive pulmonary immunity against helminths." (PMID 34324507, 2021). "Through both proteomic and transcriptomic approaches, we provide new insight into the contribution of IL-13 to pulmonary helminth infections, in particular suggesting a broader role for IL-13 in overall type 2 immunity during acute lung injury." (PMID 34127548, 2021). "Group 2 innate lymphoid cells (ILC2s) are early effectors of mucosal type 2 immunity, producing cytokines such as interleukin (IL)-13 to mediate responses to helminth infection and allergen-induced inflammation." (PMID 34484215, 2021). "The immune environment in helminth infection is often characterized as T helper 2 (Th2) biased and involves the orchestration of cytokines (IL-4, IL-5, IL-13), antibodies, and regulatory cells." (PMID 33737927, 2021). "The production and optimal affinity of these isotypes largely depends on the presence of IL-4-expressing Tfh cells in the context of helminth infection and IL-13-producing Tfh cells in the context of high-affinity IgE after allergen challenge." (PMID 34106992, 2021). "We show that IL-13+ ILC2s increase their speed and range of movement following helminth infection in both tissues, but that prolonged T cell contacts are only observed within the mucosa and not within lymphoid tissues." (PMID 34484215, 2021). "The canonical cytokines of type 2 immune response, IL-4 and IL-13, involving helminth infection and allergic disorders, are the most important cytokines responsible for inducing alternative activation of macrophages." (PMID 32575834, 2020). "IL4 has distinct functions in helminth infections but there is considerable redundancy with IL13, IL5 and IL9, whose contributions also vary among systems and parasite species/strains." (PMID 33226981, 2020). "Basophils are granulocytes that produce type-2 cytokines including IL-4, IL-5, and IL-13 in addition to histamine, leukotrienes, and prostaglandins during degranulation as a result of helminth infection." (PMID 33193446, 2020). "It has been demonstrated that stimuli such as CSF-1, IL-4, IL-10, TGF-β, IL-13, fungi, and helminth infections favor M2 subpopulation polarization, delivering IL-10 in high concentrations, and IL-12 in low amounts." (PMID 32258161, 2020). "The cytokines interleukin (IL)-4 and IL-13, signaling via the IL-4 receptor (IL-4R), orchestrate type 2 immunity to helminth infections and toxins." (PMID 32139893, 2020). "Second, while IL-4 is the dominant cytokine produced in lymphoid tissues during helminth infection, IL-13 appears to be more restricted to immune cells residing in mucosal tissues." (PMID 32793230, 2020). "Although IL-4, IL-5, and IL-13 are responsible for the majority of type-2 immune hallmarks observed during helminth infection, IL-9 has been described to have additional effects on worm clearance." (PMID 32793230, 2020). "Type 2 ILC (ILC2) are comparable to T helper 2 cells found in the adaptive immune system, which secrete cytokines such as interleukin 5 (IL‐5) and IL‐13 and have been found to play roles in host defense against helminth infections and in allergic responses." (PMID 31742928, 2020). "Coinfected mice had significantly higher IL-13 expression within lung tissues when compared with helminth infection alone." (PMID 31673002, 2019). "Nonetheless, helminth infections or their products induce a type 2 immune response, which produces cytokines, such as IL‐4, IL‐5 and IL‐13." (PMID 31496071, 2019). "ILC2s are present within visceral adipose tissue (VAT), where they are the predominant producers of IL-5 and IL-13 at homeostasis and following prolonged exposure to IL-33 or helminth infection." (PMID 30792718, 2019). "Th2 cells remain a minor population of IL-5 and IL-13 producing cells within the VAT even during helminth infection." (PMID 30792718, 2019).
helminth infection (continued). "The IL-4, IL-5, IL-13, are cytokines typically associated with a T helper 2 (TH2) response, the predominant protective immune response against helminthic infections." (PMID 30870421, 2019). "IL-9 functions as a central autocrine survival factor for ILC2 that initiate and amplify the adaptive type 2 immune response during helminth infection and allergic inflammation via production of IL-13 and IL-5, as demonstrated in C57BL/6 mice." (PMID 29872093, 2018). "Although basophils are an important source of IL-4 and IL-13, they have been shown to be dispensable in the generation of the Th2 response in some helminth infections [e.g., during Nippostrongylus brasiliensis infection in basophil-deficient mice (Mcpt8-cre)]." (PMID 29670630, 2018). "Helminth infections are usually associated with Th2-type immune response characterized by the activation of CD4+ T helper cells and secretion of IL-4, IL-5, IL-9 and IL-13." (PMID 30189894, 2018). "While IL-4 has been correlated with a protective effect during fungal reinfection, IL-13 is known to promote intestinal goblet cell hyperplasia and increased mucin expression during parasitic helminth infections." (PMID 30555491, 2018). "Several groups reported differences in Th2 inflammatory responses in allergic lung inflammation and worm infection models using the IL-4 and IL-13 knockout and transgenic mice." (PMID 29868002, 2018). "It is known that, N1 neutrophils preferentially express IL-12 in response to lipopolysaccharide, whereas N2 neutrophils express IL-33 and IL-13 in response to helminth infections." (PMID 29762526, 2018). "Interleukin(IL)-4 and IL-13 can induce alternative activation of Mφ populations in diverse tissue sites during helminth infections via the IL-4 receptor (IL-4R)." (PMID 29547639, 2018). "Helminth infections induce strong type 2 cell-mediated immune responses, characterized among other things by production of high levels of interleukin- (IL-) 4 and IL-13." (PMID 30057915, 2018). "In the case of chronic and repeated helminth infections, and corresponding Th2 type immune responses, IL-13 production can become pathological." (PMID 28542260, 2017). "Mast cells can also release IL-33 upon antigen-specific IgE-mediated activation and in response to extracellular ATP, which in turn activates ILC2s to produce IL-13 resulting in clearance of helminth infection." (PMID 29163497, 2017). "Upon stimulation with IL-25, IL-33, or thymic stromal lymphopoietin (TSLP), ILC2 can produce IL-5, IL-13, and IL-4, similar to Th2 cells, which contribute to the control of helminth infection and pathology of allergic inflammation." (PMID 29354125, 2017). "These cells are widely distributed and expand after helminthic infection and secrete IL13 resulting in worm clearance." (PMID 29081776, 2017). "During helminth infections, there is a predominant Th2 response characterized by a high production of IL-4, IL-5, IL-9, IL-10 and IL-13 cytokines." (PMID 27783986, 2016). "Our findings expand on this understanding by demonstrating that production of SP-D following helminth infection is significantly dependent on key protective immune responses against N. brasiliensis; namely IL-4/IL-13 signaling via IL-4Rα." (PMID 26900854, 2016). "Here the authors show that activation of Type 2 immunity by helminth infection counteracts the development of inflammatory arthritis, a type 17-mediated pathology, via IL-4/IL-13- STAT6 signalling and eosinophil activation." (PMID 27273006, 2016). "In parasitic infections, ILC2s have been described in experimental models of helminth infections demonstrating their role as an early source of the cytokine IL-13 and in worm expulsion." (PMID 25799270, 2015). "They expand strongly in vivo in response to IL-25 and IL-33, and represent the predominant early source of IL-5 and IL-13 during allergic inflammation and worm infection." (PMID 25659095, 2015).
helminth infection (continued). "Mice with selective deletion of IL-4/IL-13 in T cells (4-13Tko mice) are unable to mount a serum IgE response and show impaired GC formation after helminth infection." (PMID 26523376, 2015). "Group 2 innate lymphoid cells (ILC2s) have been shown to release IL-13 in response to helminth infection and recently the importance of ILC2s for the efficient development of Th2 cell responses during a Nb infection was demonstrated." (PMID 25474738, 2014). "Helminth infections, by their nature, lead to potent induction of Th2 responses (acutely) characterized by increased IL-4, IL-5, and IL-13 and—over time—to an expansion of Tregs." (PMID 24728010, 2014). "Further, helminth infections induce the production of Th2 related cytokines, such as IL-4, IL-5, IL-9 and IL-13, with anti-inflammatory qualities." (PMID 23782752, 2013). "In chronic human and experimental infections, Schistosoma mansoni, like all helminth infections, induces a predominantly Th2 immune response, characterized by interleukin-4, IL-5, IL-9, IL-10 and IL-13, antibody (IgE and IgG4), eosinophils and mast cells." (PMID 23849678, 2013). "IL-33, a proposed alarmin, stimulates innate immune cells and Th2 cells to produce IL-13 and is rapidly upregulated upon antigen exposure in murine helminth infection." (PMID 23521712, 2013). "Nuocytes have been described recently as the main innate IL-13-producing cell type that is critical for the development of type-2 immune responses in helminth infection and allergic lung inflammation." (PMID 22539101, 2012). "Previous studies on murine systems have shown that IL13 can complement IL4 or play an alternative or even stronger role in helminth infections." (PMID 22253585, 2012). "Conventional AAMΦ observed following helminthinfection are IL-4/IL-13-dependent, and analyses of the DEC mRNA transcript levelsdemonstrated that the AAMΦ-like population was absent in 4xIL-4Rα−/− mice." (PMID 21445234, 2011). "Helminth infections seemed to influence IL-12, IL-13 and TGF-β production under stimulation with both malaria Ags." (PMID 20856680, 2010). "More specifically, helminth infections tend to promote a type 2 bias in the immune response, involving the production of the cytokines interleukin-4 (IL-4), IL-5, IL-10, and IL-13, as well as immunoglobulin E." (PMID 17083720, 2006). "In the context of helminth infections, Lck has also been identified as an immunomodulator of the immune system by promoting the T-helper-2 immune response characterized by the secretion IL-4, IL-5 and IL-13." (PMID 40725160, 2025). "Helminth infections are well known to induce Th2 and regulatory immune polarization, characterized by increased IL-4, IL-5, IL-10, and IL-13 production and expansion of T regulatory cells, which suppress Th1/Th17 effector responses critical for antimycobacterial immunity." (PMID 41583474, 2025). "Indeed, IL-4 and IL-13 signaling via the type 2 receptors orchestrate type 2 immunity to helminth infections and can curtail chemotaxis and several effector functions of neutrophils in mice and humans, thereby mitigating detrimental tissue damage." (PMID 40586608, 2025). "All support the well-established type 2 hypothesis in helminth infections, marked by an increase in Th2 type cytokines such as IL-4, IL-5, and IL-13 in mucosal tissue of the bladder in response to Sh eggs as well as systemically and in lymphoid tissue." (PMID 39250522, 2024). "Helminth infections typically induce modified type 2 immune responses, characterized by the release of effector cytokines interleukin (IL-) 4, IL-5, and IL-13 from Th2 cells and type 2 innate lymphoid cells (ILC), and by heightened production of anti-inflammatory IL-10 by regulatory T (Treg) cells." (PMID 39140728, 2024). "Ym1 protein is expressed gene in helminth-activated macrophages and may be activated by helminth infection independently of IL4/IL13 signaling." (PMID 38511816, 2024).
helminth infection (continued). "During helminth infections, neutrophils may exhibit the expression of IL-13 and IL-33 and fall into the category of N2 neutrophils, although further in vivo experiments are necessary to validate this occurrence." (PMID 38203591, 2023). "Additionally, MCs have been shown to secrete IL-4 and IL-13, however, the functional roles of mast cell-derived type 2 cytokines in trained immunity during allergy or helminth infection warrants further investigation." (PMID 36065058, 2022). "Group 2 innate lymphoid cells (ILC2) are innate cells of lymphoid origin that develop from a common lymphoid progenitor and play pivotal roles in immune protection against helminth infection by secreting type 2 cytokines such as interleukin (IL)-4, IL-5, IL-9, and IL-13." (PMID 36109558, 2022). "As a result, IL-5 and IL-13 levels can rise within hours of helminth infection." (PMID 36187827, 2022). "Furthermore, our results revealed that Adrb2−/− mice infected with C. sinensis showed significantly lower production of type 2 cytokines, in particular, IL-4 (P<0.001) and IL-13 (P<0.01), compared to that observance in Adrb2+/+ mice with worm infection." (PMID 34733286, 2021). "ILC2s are essential for control of helminth infections and tissue repair and are involved in pathogenesis of asthma and allergy by secretion of type 2 cytokines IL-5, IL-9 and IL-13." (PMID 34938670, 2021). "With regard to the IL13-1055 and IL13-591 polymorphisms, higher prevalences of STH infections were observed among pupils with genotypes bearing the IL13-1055C and the IL13-591A alleles, suggesting likely IL-13 gene polymorphism influence on STH and other helminth infection levels as well." (PMID 34185775, 2021). "Although it is clear that smooth muscle cells respond to IL-4/IL-13 in helminth infections, whether this influences the outcome in ulcerative colitis has not been studied." (PMID 32410852, 2020). "Alterations in intestinal mucus production and glycosylation are known to occur during gastrointestinal helminth infections and, given the essential role of the IL-4/IL-13 pathway in goblet cell hyperplasia, mucus secretion and glycosylation, are likely to arise during intestinal schistosomiasis." (PMID 33329584, 2020). "Reduced egg burden can be explained because increased H4Ac in IL13 may facilitate higher IL-13 production and suggests that this gene is sensitive to and modified by helminth infection." (PMID 32425942, 2020). "Although IL-13 likely plays a role within pathogenic IgE response to allergens, it does not appear to affect the production of IgE during acute helminth infection." (PMID 32793230, 2020). "Helminth infections are a global health burden in humans and livestock and are considered to be a major evolutionary driver of type 2 immunity (orchestrated by type 2 cytokines, e.g., IL‐4 and IL‐13)." (PMID 31267552, 2019). "In general, helminth infections commonly induce a strong Th2 response, which is orchestrated by many different cell types and characterised, among others, by the secretion of IL-4, IL-5 and IL-13." (PMID 31315623, 2019). "However, as shown for helminth infections and in anti-tumor responses, Irf4−/− mice showed hampered M2 macrophage polarization, when stimulated with IL-4 and IL-13 ex vivo." (PMID 31632388, 2019). "Type 2 immune response, featured by elevation of IL-4 and IL-13 levels, plays a crucial role in host protection as well as pathological tissue fibrosis after helminth infection, including schistosome infection, but the signals that induce type 2 immunity are poorly understood." (PMID 29554131, 2018). "Although these papers described the differential production of and dependence on IL-4 and IL-13 in many of the phenotypic endpoints of Th2-mediated inflammation to allergen challenge or worm infection, few if any described the upstream signaling differences elicited by the two cytokines." (PMID 29868002, 2018).